COL10A1 (collagen type X alpha 1 chain)
Diseases named in the same sentence as COL10A1 in open-access papers (continued):
Sharing a sentence is not in itself a finding about the gene and the disease.
COVID-19 (2 papers, 2023 to 2024). A disease caused by infection with severe acute respiratory syndrome coronavirus 2. "The AUC values for these genes in depression patients surpassed 0.8, and those in COVID-19 patients exceeded 0.7, with the exception of COL10A1, SPSB4, and SLC10A2, whose AUC values were less than 0.7." (PMID 39588145, 2024). "The proteins COL10A1/FAP/FN1 were found to be common signature genes for COVID-19 and PC, were significantly up-regulated in both diseases and showed good diagnostic efficacy for PC." (PMID 38063927, 2023). "Then, COL10A1/FAP/FN1 were defined as the common signature genes of COVID-19 and PC in this study." (PMID 38063927, 2023). "The upregulated expression of COL10A1/FAP/FN1, the characteristic genes of COVID-19, are potential diagnostic targets for PC, and the upregulated expression of FN1 may promote the progression of PC by activating the PI3K-AKT signaling pathway." (PMID 38063927, 2023). "The clustering typing based on the expression levels of COL10A1/FAP/FN1 of COVID-19 signature genes provides a new typing approach for PC, enabling a more refined analysis of PC and providing a good reference for the sophisticated treatment of PC and further clinical studies." (PMID 38063927, 2023).
Hip dysplasia (2 papers, 2018 to 2025). The presence of developmental dysplasia of the hip. "In 3-week-old MCDS mice with Col10a1 p.N617K mutation, 3-week CBZ treatment (250 mg/kg/d) significantly reduced the width of the hypertrophic zone, increased femur and tibia growth, and alleviated hip dysplasia." (PMID 41454937, 2025).
keloid (2 papers, 2020 to 2023). An irregularly shaped, elevated mark on the skin caused by deposits of excessive amounts of collagen during wound healing. "According to the findings of RNA sequencing, COL5A2, COL10A1, and COL11A1 have been reported to be upregulated in keloid, as in our study." (PMID 37082197, 2023). "In our present study, we screened bone/cartilage-related genes (COMP, ASPN, COL5A2, COL10A1, and COL11A1), transcription factor (FOXC1), and miRNA (miR-335-5p) in major fibrotic skin diseases including keloid and SSc." (PMID 37082197, 2023). "The top 50 DEGs in lesional versus normal skin comparison included products related to fibrosis and cartilage/bone-differentiation (ADAM12, ASPN, COL10A1, COL11A1, FBN2), previously reported to be dysregulated in keloids." (PMID 33329590, 2020).
metaphyseal chondrodysplasia (2 papers, 2022). "In conditions with reduced penetrance, as described for COL10A1-related metaphyseal chondrodysplasia (OMIM #156500), the causative variants are also subject to comparatively less selective pressure." (PMID 36672771, 2022). "COL10A1 plays a considerable role in endochondral ossification, possibly related to matrix degradation, calcification, vascular invasion, and mutations in this gene are associated with metaphyseal chondrodysplasia." (PMID 36246404, 2022).
osteopetrosis (2 papers, 2021 to 2022). Osteopetrosis, also known as marble bone disease, is a descriptive term that refers to a group of rare, heritable disorders of the skeleton characterized by increased bone density on radiographs. "The deletion of RANKL in hypertrophic chondrocytes by Col10a1-Cre30 resulted in severe osteopetrosis due to a reduction of osteoclast number in the bone marrow." (PMID 35851381, 2022). "In contrast, the Col10a1-Cre;Ctnnb1EX3fl/fl;ROSA26R-Tomato (X/ΔEXTomato) mice with stabilized β-catenin showed delayed primary ossification and developed an osteopetrosis-like phenotype after birth, opposite of the X/CKOTomato mice." (PMID 34021120, 2021).
prostate adenocarcinoma (2 papers, 2023). "Finally, Gene Expression Omnibus (GEO) datasets were utilized to validate COL10A1 expression levels in Prostate adenocarcinoma (PRAD)." (PMID 38147021, 2023).
pterygium (2 papers, 2022 to 2025). A wedge-shaped fibrovascular lesion arising from the bulbar conjunctiva and extending to the cornea. "The upregulation of this gene was followed by that of genes involved in the extracellular matrix structure, COL10A1, and remodeling, MMP9, reflecting intensive fibrosis, the main pathological finding of pterygium." (PMID 40243577, 2025).
pulmonary fibrosis (2 papers, 2022 to 2025). Chronic progressive interstitial lung disorder characterized by the replacement of the lung tissue by connective tissue, leading to progressive dyspnea, respiratory failure, or right heart failure. "However, we have not found that the characteristic gene COL10A1 identified in this study has been involved in pulmonary fibrosis." (PMID 36507532, 2022).
triple-negative breast carcinoma (2 papers, 2020 to 2024). An invasive breast carcinoma which is negative for expression of estrogen receptor (ER), progesterone receptor (PR), and human epidermal growth factor receptor 2 (HER2). "Besides, we found that COL10A1 was strongly elevated in non-basal-like subtype with respect to basal-like subtype; the same pattern of change was also observed in triple-negative breast cancer (TNBC) patients." (PMID 32043519, 2020).
amoebiasis (1 paper, 2022). "In detail, COL1A2, COL1A1, and COL10A1 were enriched in protein digestion and absorption; COL1A2, COL1A1, and SPP1 were enriched in ECM-receptor interaction, focal adhesion, and PI3K-Akt signaling pathway; COL1A2 and COL1A1 were further enriched in amoebiasis (P < 0.05)." (PMID 35726219, 2022). "The prime module in protein-protein interaction network of DEGs, including ADAMTS2, COL10A1, COL1A1, COL1A2, COL8A1, BGN, and SPP1, was enriched in protein digestion and absorption, ECM-receptor interaction, focal adhesion, PI3K-Akt signaling pathway, and amoebiasis." (PMID 35726219, 2022).
campomelic dysplasia (1 paper, 2011). "A role for SOX9 as transcriptional repressor of Col10a1 in non-hypertrophic chondrocytes is consistent with the observation that COL10A1 expression was up-regulated in cartilage isolated from SOX9 haploinsufficient campomelic dysplasia patients." (PMID 22072985, 2011).
cervical squamous cell carcinoma (1 paper, 2023). A squamous cell carcinoma arising from the cervical epithelium. "POSTN + fibroblasts showed high expression levels of several ECM remodeling genes (MMP11, CTHRC1, COL1A1, COL1A2, COL3A1, COL10A1, and COL11A1) and enriched signatures of ECM, which were consistent with the previously reported matrix CAFs (mCAFs) in cervical squamous cell carcinoma (CESC)." (PMID 37833788, 2023).
chronic lung disease (1 paper, 2025). According to the definitions of the American and British Thoracic Societies, including pulmonary functional tests, X-rays, and CT scans for items such as fibrosis, bronchiectasis, bullae, emphysema, nodular or lymphomatous abnormalities. "In summary, we have explored the crucial roles of angiogenesis and immunity in the onset and progression of ILD and COPD, and we identified COL10A1, EDN1, MMP1, and RRAS as potential novel therapeutic targets for chronic lung diseases." (PMID 40002743, 2025).
Cleidocranial Dysplasia (1 paper, 2017). "Abnormal COL10A1 expression and diverse mutations have been observed in multiple skeletal diseases, such as Cleidocranial Dysplasia (CCD), SMCD and SMD, implying a role of COL10A1 variants in KBD." (PMID 28651521, 2017).
collagenopathy (1 paper, 2021). "Our findings suggest that these candidate Col10a1 transcriptional regulators, including Tbx5, are potential therapeutic targets in collagenopathy and skeletal diseases associated with abnormal Col10a1 expression and chondrocyte hypertrophy." (PMID 34276786, 2021).
congenital muscular dystrophy (1 paper, 2024). A muscular dystrophy that is characterized by diminished muscle tone (hypotonia), progressive muscle weakness and degeneration (atrophy), abnormally fixed joints, spinal rigidity, and delays in reaching motor milestones such as sitting or standing unassisted. "Mutations within COL10A1 in sheep have been linked to specific muscle disorders, including congenital muscular dystrophy." (PMID 39457877, 2024).
disc degeneration (1 paper, 2021). "In some experiments on mice that have led to disc degeneration, abnormal expression of type X collagen, increased apoptosis, inappropriate intervertebral disc ossification, and elevated expression of COL10A1, Runx2, MMP-13, etc. were observed in degenerative NP." (PMID 34307661, 2021).
ductal carcinoma in situ (1 paper, 2025). "Pathological classification of hematoxylin and eosin (H&E)-stained spatial regions reveals that COL10A1 is most highly expressed in stromal, lymphocytic, and invasive carcinoma regions, and rarely expressed in adjacent ductal carcinoma in situ, adipose tissue, or normal breast tissue regions." (PMID 39939916, 2025).
endometrial cancer (1 paper, 2023). Primary or metastatic malignant neoplasm involving the endometrium (mucous membrane that lines the endometrial cavity). "In our present work, we found that mutations in COL10A1 were most commonly found in endometrial cancer (>10%)." (PMID 38147021, 2023).
fibrosis (1 paper, 2025). the formation of excess fibrous connective tissue in an organ or tissue in a reparative or reactive process. "In fibrosis, COL10A1 interacts with the integrin subunit β1 (ITGB1), which not only strengthens cell–ECM adhesion but also triggers the TGFβ signaling pathway." (PMID 40002743, 2025).
glomerulosclerosis (1 paper, 2024). A hardening of the kidney glomerulus caused by scarring of the blood vessels. "Masson’s trichrome staining revealed that COL10A1 silencing attenuated glomerulosclerosis and interstitial fibrosis." (PMID 38345033, 2024). "In contrast, the degrees of glomerulosclerosis and interstitial fibrosis were attenuated in the I/R + si-Col10a1 group." (PMID 38345033, 2024).
Huntington disease (1 paper, 2023). Huntington disease (HD) is a rare neurodegenerative disorder of the central nervous system characterized by unwanted choreatic movements, behavioral and psychiatric disturbances and dementia. "The bubble plot also revealed that KEGG terms, such as ribosome, spliceosome, and Huntington’s disease enriched in the co-expression group negatively correlated with COL10A1." (PMID 37006317, 2023).
hypophosphatemic rickets (1 paper, 2021). Rickets due to low serum phosphate concentrations, the cause of which can be nutritional or genetic. "Heterozygous variants in COL10A1 gene were detected in 2/15 probands suspected to have hypophosphatemic rickets, and no candidate gene was found in the other 13 probands." (PMID 34557487, 2021).
invasive carcinoma (1 paper, 2025). A carcinoma that is not confined to the epithelium, and has spread to the surrounding stroma. "This module was reported to be most highly expressed in invasive carcinoma, stromal, and lymphocytic regions by spatial transcriptomic analysis, further supporting the utility of COL10A1 and our BRCA ColX module in highlighting aggressive tumor stromal regions." (PMID 39939916, 2025).
liver cancer (1 paper, 2021). An epithelial or non-epithelial malignant neoplasm that arises from the liver. "Interestingly, we found that most of these key node genes play important roles in tumorigenesis (RET, CEACAM5), immune regulation (CTSG, CD79A) and the EMT pathway (COL10A1, COL11A2), suggesting their significant role in the recurrence of liver cancer." (PMID 34956309, 2021).
Metaphyseal dysplasia (1 paper, 2021). The presence of dysplastic regions in metaphyseal regions. "Mutations in the Collagen X gene (COL10A1) lead to various forms of metaphyseal dysplasia." (PMID 33461534, 2021).
metastatic tumors (1 paper, 2018). "In our study, we further found that the high protein expression of CD31 and CD34 (angiogenesis markers) was consistent with the high protein expression of COL10A1 in the peritoneal metastatic tumors of GC patients." (PMID 30154451, 2018). "The IHC assay of lung metastatic tumors revealed that knockdown of COL10A1 enhanced the expression of E-cadherin (epithelial marker) and decreased the expression of Vimentin (mesenchymal marker), while there was not significant decrease in SOX9 expression." (PMID 30154451, 2018). "Furthermore, we detected the protein expression of SOX9, COL10A1, Ki-67 (cell proliferation marker), CD31 and CD34 (angiogenesis markers) in peritoneal metastatic tumors of GC patients." (PMID 30154451, 2018).
osteogenesis imperfecta (1 paper, 2022). Osteogenesis imperfecta (OI) comprises a heterogeneous group of genetic disorders characterized by increased bone fragility, low bone mass, and susceptibility to bone fractures with variable severity. "The two VUS were paternally inherited missense variants in the COL1A1 gene related to autosomal dominant forms of osteogenesis imperfecta (OMIM 166210) and paternally inherited nonsense variant in the COL10A1 gene related to autosomal dominant metaphyseal chondrodysplasia Schmid type (OMIM 156500)." (PMID 36360323, 2022).
osteoporosis (1 paper, 2022). A condition of reduced bone mass, with decreased cortical thickness and a decrease in the number and size of the trabeculae of cancellous bone (but normal chemical composition), resulting in increased fracture incidence. "Comparing the transcriptome profiles of osteoblasts during bone remodeling under osteoporosis-like conditions and fin regeneration, we identified a significant up-regulation of mmp13b in col10a1 positive osteoblast progenitors." (PMID 35281094, 2022).
pneumonitis (1 paper, 2022). An inflammatory process affecting the lung parenchyma. "Several of these filtered candidates were found to be secreted (C12orf49, COL10A1, FNDC4, ITLN2, MATN3, PDZD2, RS1, SCRG1, and ST6GALNAC5) making them potential candidate biomarkers useful for distinguishing IPF from pneumonitis." (PMID 35628257, 2022).
steatosis (1 paper, 2025). Increased lipid within the cytoplasm of cells. "Histopathological evaluation via H&E staining confirmed MASLD-associated steatosis and fibrosis, while IHC revealed that TPPP3 and COL10A1 localized to fibrotic septa and peri-sinusoidal regions, with staining intensities strongly correlated with fibrosis severity." (PMID 40380802, 2025).
systemic lupus erythematosus (1 paper, 2024). An autoimmune multi-organ disease typically associated with vasculopathy and autoantibody production. "COL10A1 exhibited associations with systemic lupus erythematosus and liver enzyme levels." (PMID 38903171, 2024).
tendinopathy (1 paper, 2023). "However, while the mRNA expression of a number of collagens was 1.6–2.7-fold upregulated in tendinopathy patients, COL1A1, COL1A2, COL10A1, and COL11A1/2 were 5.3–15.2-fold upregulated in tetraplegic CP patients, suggesting strongly increased collagen synthesis." (PMID 38001919, 2023).
tumor (71 papers, 2014 to 2026). "Combined with the IHC observation that ColXα1 is expressed in tumor stroma, these findings suggest that COL10A1 expression is associated with an oncogenic fibroblast environment." (PMID 39939916, 2025). "Multiple studies have revealed that COL10A1 is closely associated with the angiogenic process in tumors, promoting tumor migration, invasion, and epithelial–mesenchymal transition (EMT)." (PMID 40002743, 2025). "We observed that COL10A1+Fib is associated with tumor metastasis and the promotion of an immunosuppressive microenvironment." (PMID 40826474, 2025). "COL10A1 from tissue and its soluble form in plasma were previously identified by us in a series of studies as being associated with early GC and tumor progression." (PMID 41303526, 2025). "SYNPO2L promotes COL10A1 secretion and infiltration of tumour-associated fibroblasts, thereby promoting epithelial-mesenchymal transition (EMT) in tumour cells, making them more likely to develop distant metastases." (PMID 40463716, 2025). "We found that SYNPO2L can affect the secretion of COL10A1 in tumor cells, thereby mediating the involvement of tumor-associated fibroblasts." (PMID 39247832, 2024). "SYNPO2L promotes the secretion of COL10A1 and the infiltration of tumor-associated fibroblasts, thereby facilitating Epithelial-Mesenchymal Transition (EMT) in tumor cells and making them more prone to distant metastasis." (PMID 39247832, 2024). "High expression of COL10A1 protein in cancer tissues has been confirmed to be associated with tumor angiogenesis in different types of cancer." (PMID 39247832, 2024). "COL10A1 protein level was also significantly associated with sex (male vs. female, P= 0.044), tumor grade (High vs. Low, P< 0.001), and pathological stage (III&IV vs. I&II, P< 0.001) in the validation cohort (n=77)." (PMID 37006317, 2023). "Higher expression of COL10A1 protein has been revealed in cancerous tissue and has been verified to be linked with tumor angiogenesis across various types of cancer." (PMID 37006317, 2023). "Immune correlation analysis of COL10A1 in various cancers showed its significant correlation with Tumor mutational burden (TMB), microsatellite instability (MSI) and immune cell infiltration." (PMID 38147021, 2023). "COL10A1 mRNA expression level was significantly associated with tumor grade (High vs. Low, P<0.001) and pathological stage (III&IV vs. I&II, P< 0.001) in the TCGA database." (PMID 37006317, 2023). "Eventually the process identifying serum levels of COL10A1 protein as a potential diagnostic candidate for the detection of adenomatous lesion and tumor." (PMID 37274780, 2023). "Elevated COL10A1 expression is associated with advanced tumor stages based on histopathological and image-based tumor staging." (PMID 36267978, 2022). "Previous studies have shown that COL10A1 is specifically expressed in the tumor microenvironment and is associated with tumor angiogenesis." (PMID 36105715, 2022). "Further analysis showed that COL10A1 expression levels were associated with M1 macrophages, M2 macrophages, tumor-associated markers of macrophage (TAM), and T-regulatory (Treg) cells." (PMID 36105715, 2022). "Co-expression of SOX9 and COL10A1 was associated with tumor progression and was strongly predictive of overall survival in GC patients." (PMID 30154451, 2018). "Increased expression of genes encoding for stromal collagens, including Col10A1, and reduced expression of immune-associated genes, reflecting lower levels of total tumor-infiltrating lymphocytes (TILs), were strongly associated with poor pathologic response." (PMID 27090210, 2016). "COL10A1 expression is increased in tumours and associated with tumour vasculature." (PMID 41303312, 2025). "Existing reports indicate that COL10A1 is highly expressed in the tumor stroma of breast, pancreatic, and gastrointestinal cancers, where its upregulation is typically associated with increased tumor invasiveness and poorer patient survival." (PMID 40826474, 2025).